B2M (beta-2-microglobulin)
Diseases named in the same sentence as B2M in open-access papers (continued):
Sharing a sentence is not in itself a finding about the gene and the disease.
cancer (continued). "More importantly, we found that the DC with MSCs did not change the NK resistance of B2M−/− cancer cells." (PMID 38638003, 2024). "Cancer cells can evade clearance by macrophages through overexpression of antiphagocytic surface proteins including CD47, programmed cell death ligand 1 (PD-L1), the beta-2 microglobulin subunit of the major histocompatibility class I complex (B2M), and CD24." (PMID 38702326, 2024). "Despite different extents of histone demethylation, B2M is overexpressed in all three murine cell lines, suggesting that αKG regulates B2M expression in a wide variety of cancer rather than limited to RCC." (PMID 37526345, 2023). "Importantly, TGF β1 targets the APM molecules in cancer cells by downregulating the H2 complex (MHC I in mouse), B2m, Tap1, and Tap2 shown in an in vitro model of CCK168 squamous cell cancer cells." (PMID 38067396, 2023). "High levels of γδ T cell infiltration were observed in cancers with B2M defects as compared to B2M-proficient cancers, albeit this difference was not significant." (PMID 36631610, 2023). "This opens perspectives for treatment of certain cancers or in allogeneic transplantation of B2M-negative pluripotent stem cells expressing a single-chain HLA-E trimer." (PMID 36518759, 2022). "Similarly, the altered frequencies of B2M and TAPBP came first and fourth among 484 samples from pan-cancer TCGA cohort." (PMID 36311733, 2022). "Non-structural mechanisms such as epigenetic silencing of B2M, HLA class I, or other antigen-processing genes are common mechanisms of immune evasion and can be seen in nearly three quarters of patients with cancer, including those with HNSCC." (PMID 36555876, 2022). "One limitation is that baseline survival data of B2M-mutant cancer patients are not available, as follow-up data were only retrieved for patients receiving ICB treatment." (PMID 34168989, 2021). "Among 4 B2M-mutant cancer patients receiving ICB, only one patient (25% as opposed to 46.6% among B2M-wild type cancer patients, p>0.99), with initial disease stabilization, showed PR on subsequent imaging as best response, the other three patients had SD." (PMID 34168989, 2021). "Genes including the HLA gene family, B2M, and IRF4 might be the key genes involved in the anticolon cancer response of CD8+ T cells by regulating cholesterol metabolism." (PMID 34858500, 2021). "In summary, genes including the HLA gene family, B2M, IRF4, and STAT5A might be the key genes involved in the anticolon cancer response of CD8+ T cells via regulation of cholesterol metabolism." (PMID 34858500, 2021). "Genes including the HLA gene family, B2M, IRF4, and STAT5A might be the key genes involved in the anticolon cancer response of CD8+ T cells through the regulation of cholesterol metabolism." (PMID 34858500, 2021). "In addition to CD29 and CD98, we also decided to test the following antigens, due to their known functions that make them candidates to be widely expressed on the cancer cell lines: CD47, B2M, and Epithelial cell adhesion molecule (EPCAM)." (PMID 33690223, 2021). "Single-cell analysis identified that CTSC and B2M were up-regulated in LNM-positive epithelial cells with strong correlation to poor DFS, suggesting that cancer-related signaling pathways such as TNF-α/p38 MAPK signaling pathway could promote LNM in PTC." (PMID 34805166, 2021). "Among the downregulated genes in the AMC-HN-8-BCL11A cells, some genes were associated with the epithelial-to-mesenchymal transition and hypoxia, including B2M, which is a Class I MHC protein that regulates the proliferation of normal cells and carcinoma cells." (PMID 32266150, 2020). "The prognostic impact of B2M has been well demonstrated in different types of cancers, but its relationship with ESCC has not been thoroughly explored." (PMID 29615660, 2018). "Previously, we also showed that expression of brachyury in carcinoma cells does not affect the levels of MHC-class I or beta-2 microglobulin expression." (PMID 29774202, 2018).
cancer (continued). "For example, in our study HRAS (P = 5.0 × 10-46), AKT1 (P = 9.5 × 10-26), PIK3CA (P = 5.5 × 10-5), B2M (P = 6.7 × 10-4), and KDM5C (P = 3.5 × 10-3) were predicted to be putative cancer genes using Fisher’s exact test and evidently designated as cancer driver genes according to the 20/20 rule." (PMID 25360158, 2014). "All genes studied achieved medium expression stability with M values ranging from 1.09 for B2M to 0.82 for GAPDH (average geNorm M≤1.0), which is typically seen when evaluating candidate reference targets on heterogeneous samples, like cancer biopsies or samples from different tissues." (PMID 25473950, 2014). "The loss of several tumor suppressor proteins by nonstop mutations, as verified for B2M, CDKN1B (p27KIP1) and MLH1 in this study, could have a relevant functional impact in cancer development and therapy." (PMID 39448564, 2024). "A similar outcome could be demonstrated in B2M, namely that B2M LOH is prevalent in cancer patients who have a poor response to or non-response to ICB therapy." (PMID 38041084, 2023). "Multiplex techniques have been developed, which allow the simultaneous elimination of TCRs, beta-2 microglobulin (B2 M), a subunit of HLA-I, and other proteins like PD-1 and CTLA-4, leading to produce allogeneic CAR T-cells, which may have higher anti-cancer property against TNBC." (PMID 37469704, 2023). "We found lots of them might play a key role in the transformation of enterocyte progenitor cells to cancer cells such as MALAT1, B2M, EEF1A1, RPL5, B3GNT7, RHOB and ACTB might play a key role in the transformation of enterocyte progenitor cells to cancer cells." (PMID 36944972, 2023). "In addition, several other anti-phagocytic surface proteins (immune checkpoint) such as PDL1, LILRB1, B2M, and CD24 have also been found to inhibit the phagocytosis of cancer cells both in the in vitro co-culture of cancer cells with macrophages as well as in vivo." (PMID 36679900, 2022). "Notably, cancer cells can escape immune surveillance by overexpression of antiphagocytic surface proteins such as CD47, PD-L1, and the beta-2 microglobulin subunits of major histocompatibility class-I (MHC-class-I) complex (B2M)." (PMID 35042862, 2022). "What may be the mechanisms responsible for a favorable clinical course of B2M-mutant cancers in the absence of ICB?" (PMID 34168989, 2021). "Based on these results, we speculate that genes including the HLA gene family, B2M, IRF4, and STAT5A that may be involved in EBV infection and cell adhesion molecule pathways play important roles in the anticolon cancer response of CD8+ T cells by regulating cholesterol metabolism." (PMID 34858500, 2021). "Several genes (B2M, EIF2B1, ELF1 and PSMC4; type 1 EC, and YWAZ, UBC, and PGK1; type 2 EC) were not identified in the combinations of five best genes for the two cancer sub-types (this study) suggesting that the transcriptome of these two EC sub-types may in fact be very different." (PMID 32439920, 2020). "Moreover, alterations in the antigen-presenting machinery, beta 2 microglobulin (B2M), or the MHC itself may make cancer cells avoid presenting antigens on the surface." (PMID 35582437, 2020). "However, many models, including murine and human, in our hands showed surface expression of MHC-I and responsiveness to IFN-γ, whereby treatment of IFN-γ resulted in increase of MHC-I surface expression, suggesting that the cancer cells did not completely lose B2M or IFN-γ pathway genes." (PMID 38011559, 2023). "Regarding the correlations between RORC expression and MHC molecules (which are closely associated with cancer occurrence and development), RORC expression exhibited the strongest positive correlation with HLA-F in ACC, and the strongest negative correlation with B2M in UVM." (PMID 36186454, 2022). "In contrast, for the three reference genes (B2M, TBP and UBC), neither or only one of the two guide RNAs (gRNAs) targeting each gene showed increased repression fold changes in cancer." (PMID 39478119, 2024).
cancer (continued). "The NKG2D ligands MICA/B and ULBPs were expressed by the cancer cell lines and the MMR-d CRC PDTOs, irrespective of their B2M status." (PMID 36631610, 2023). "While B2M and CD298 are useful for human samples, there are no validated markers that are robustly expressed by commonly used mouse cancer cell lines (e.g., MC38, CT26, B16, KPC, and Panc02), which are critical components of many syngeneic immunocompetent studies." (PMID 33690223, 2021).
infection (64 papers, 2008 to 2026). The state of being infected such as from the introduction of a foreign agent such as serum, vaccine, antigenic substance or organism. "At the same time, β2-microglobulin (B2M), as an immune response marker, tends to increase in the infections and inflammation caused by common bile duct stones." (PMID 40551898, 2025). "Knockout of FCGRT and B2M, which encode the two subunits of FcRn, prevented infection by E18 and other echoviruses in the same physiological cluster." (PMID 35862785, 2022). "All the data were analyzed using the model-based analysis of genome-wide CRISPR/Cas9 knockout (MAGeCK) method; FCGRT and B2M, the two genes encoding the FcRn subunits, were identified as the essential genes for E18 infection." (PMID 35862785, 2022). "Targeting of the known ACE2 receptor by CRISPR-Cas9 led to a near-complete loss of infectivity (two-way ANOVA of ACE2 infection vs B2M control Bonferroni-corrected p-value < 0.001), despite these cells retaining very high expression of BSG." (PMID 33432067, 2021). "An increased antibacterial activity of B2M was observed at acidic pH values that are a hallmark for infection and inflammation." (PMID 33092477, 2020). "Investigating pH dependency of the antimicrobial activity of B2M demonstrated an increased activity at pH values of 5.5 and below, a hallmark of infection and inflammation." (PMID 33092477, 2020). "B2m−/− neonates were more susceptible to lethal infection and, notably, most deaths occurred prior to 14 days post infection—i.e., well before the time that CD4−/− neonates begin to succumb." (PMID 28119902, 2016). "In CD8+ T cell-deficient beta 2-microglobulin knockout mice, bacterial replication was uncontrolled, and all mice succumbed to the infection, despite higher serum IFN-γ levels and stronger macrophage responses in liver and lung." (PMID 27606708, 2016). "B2m−/− neonates were more susceptible to infection, compared with wt neonates, indicating that CD8+ cells were required for survival of primary infection." (PMID 28119902, 2016). "The pathway analysis based on the KEGG database revealed that many immune-related and infection-related pathways were enriched, also suggesting that insufficiency of B2M and CIITA genes may make pigs susceptible to pathogenic microorganisms." (PMID 35573408, 2022). "Due to its antigen presentation role in APCs, B2M-knockout in animal models indicates that immune cells, except for those carrying the T-cell receptor type, can also play an important role against pathogenic infection." (PMID 34199259, 2021). "To summarize, the abnormal expression of CXCL10, ICAM1, CD40, IRF7, and B2M may be the main cause of tracheal dysfunction after infection with coronavirus." (PMID 34504502, 2021). "Interestingly, when immune cells are activated due to inflammation, infection, injury, or pregnancy, under the influence of cytokines and chemokines, not only are B2m-free HC HLA variant molecules (Faces 2–4) upregulated but different KIR molecules are as well." (PMID 37627243, 2023). "Notably, published results on experimental infections of B2M deficient mice reported unexpected levels of resistance to VV, phenotypes that now might be reasoned to be influenced by B2M absence." (PMID 36574441, 2022). "H1N1-GFP (PR8 H1N1) infection increased GFP+ primary human PMVECs and MHC-I (HLA-A/B2M) expression at 24 hours post infection (hpi), indicating successful cell infection and activation." (PMID 41542053, 2026). "In certain disease states, such as infection triggered by common bile duct stones, increased lymphocyte proliferation leads to enhanced B2M synthesis." (PMID 40551898, 2025). "MA10 infection resulted in six additional down-regulated (Cpe, B2m, Pltp, Sparc, Cldn5, Vtn) and four up-regulated DEGs (Slc2a1, Vim, Apod, Acta2), whereas Aβ pathology alone produced one down-regulated (Slc2a1) and three upregulated DEGs (Gfap, Psen1, Clu)." (PMID 41497643, 2025).
infection (continued). "Factors predicting the risk of infection in this study were ECOG performance status, beta-2 microglobulin, LDH, and hemoglobin values." (PMID 38062124, 2024). "In particular, we found increased TGF-β1, FGF23, NGAL, IL-18, HIF1-α, TLR2, YKL-40, and B2M mRNA levels long-term post MHV-1 infection." (PMID 37626956, 2023). "SARS-CoV-2 natural infection alters B2M expression, partially demonstrating the differential expression of B2M after vaccination." (PMID 36936955, 2023). "In contrast to myeloid cells, DCs, and ECs, we only detected few transcripts that are significantly elevated with infection in T cells including B2m, Satb1, Gm42418, Gimap6 in CD4+ T cells and Gm42418 in CD8+ T cells." (PMID 35789215, 2022). "We found approximately 50% of VV particles colocalizing with B2M at 0, 15, 30, 45 and 60 min post infection." (PMID 36574441, 2022). "In the knock-in experiment, AAV1/2 was added for infection promptly after double strand breaks were generated in the B2M sequence in the genome of UC-MSCs using CRISPR/Cas9." (PMID 36313397, 2022). "As expected, the B2M reference gene was again found to be expressed at similar levels throughout the infection period." (PMID 36298701, 2022). "As the specific role of B2M in early VV infection is related with the early steps of infection, we tested the degree of colocalization of B2M and VV at cell membrane." (PMID 36574441, 2022). "Low multiplicity infections (m.o.i. = 0.05) of those clones led to a decrease in progeny virus, indicating an effect of B2M absence on VV infection." (PMID 36574441, 2022). "Second, B2M role is relevant during early infection stages, since early gene expression was clearly diminished." (PMID 36574441, 2022). "The ubiquitin system has been extensively studied for its importance during infection, and its relationship to B2M is hence intriguing in view of our results." (PMID 36574441, 2022). "Existing evidence has suggested that B2M is probably a general biomarker that reflects the acute or chronic changes during inflammation, infection, or immune dysregulation." (PMID 33581388, 2021). "Response to stress (MT1X), repair process (DCLRE1A), and T cell activation-related genes (B2M) were the most important upstream regulators during the decline phase of the gt3 infection." (PMID 32877413, 2020). "B2M in CSF proved to be an effective biomarker of CNS inflammation and infection in our population, although our study was retrospective in nature and included a small population with a high prevalence of CNS inflammation (31%) and infection (17%)." (PMID 31063510, 2019). "Neopterin and beta 2 microglobulin are produced by monocytes and macrophages in response to infection and are proposed to be surrogate markers for T cell and lymphocyte activity." (PMID 30850976, 2019). "The results from this analysis showed that only B2M was stably expressed across the different time points in both the control and the infection group." (PMID 30545363, 2018). "Only 3 genes each in the spleen (B2m, Lst1 and Edf1) and the brain (Six6, Cd163 and Bmp10) were modulated at all three time points after V3034 infection." (PMID 28446152, 2017). "An enzyme linked immunosorbent assay (ELISA) was performed for evaluation of CRP, B2M and Neopterin levels and correlated with clinical and microbiological parameters including strain of infection." (PMID 26951717, 2016). "Several proteins with significant SVVs identified from the network structure variations during infection are involved in the immune response, such as Tlr2 and B2m." (PMID 24757665, 2014). "Cytokines like CCL5, small inducible cytokine A2, IL8 and other immune responsive genes like STAT1, IRF1 and B2 M were found to be up-regulated at this time point post infection with seasonal influenza virus." (PMID 21439068, 2011). "Other genes involved in immune response which were up regulated in all time point of infection were Mpa 21, Mx2, Mx1 Phf11, Tgtp, B2 m and Tap1." (PMID 21371334, 2011).